CD74 (CD74 molecule)
Diseases named in the same sentence as CD74 in open-access papers (continued):
Sharing a sentence is not in itself a finding about the gene and the disease.
breast carcinoma (continued). "Expression of CD74, a chaperone protein with an important role in innate immunity, in breast cancer tissue is correlated with increased metastasis." (PMID 31308057, 2019). "We report the physical association of CD74 and CD44 and consider their likely function in breast cancer cells." (PMID 29190904, 2017). "Given this dichotomy we set out to examine the relationship between CD74 and outcomes in breast cancer." (PMID 27058619, 2017). "Coordinate expression of HLA-DR, CD74 and HLA-DM by tumour cells is thought to be an indicator of improved prognosis in breast carcinoma." (PMID 29190904, 2017). "In the present study, our results showed that CD74 was more highly expressed on the membrane and in the cytoplasm of breast cancer tissues than in control breast tissues." (PMID 27626171, 2016). "Taking these findings together, our study suggests that CD74 promotes CFL1 phosphorylation in breast cancer cells." (PMID 27626171, 2016). "The analysis of clinical data indicated that CD74 expression correlated with clinical stages and lymph node metastasis in breast cancer." (PMID 27626171, 2016). "CD74 has a low expression level in normal epithelial cells but is highly expressed in a variety of tumor cells, including breast cancer cells." (PMID 27626171, 2016). "The IHC results showed that CD74 was highly expressed on the membrane and in the cytoplasm of breast cancer tissues compared with control breast tissues." (PMID 27626171, 2016). "Different expression levels of CD74 were detected in different breast cancer cell lines by western blotting." (PMID 27626171, 2016). "CD44 also has an effect on cell morphology, and the breast cancer cells with CD74 or/and CD44 knockdown exhibited a smoother cell edge with fewer protrusions." (PMID 27626171, 2016). "Looking at a receptor, CD74 is expressed in breast cancer tissue and its presence appears to be correlated with lymph node invasion and triple-negative tumors making a correlation study attractive." (PMID 24939415, 2014). "Following profiling of MIF expression, we proceeded to map CD74 in breast cancer and in tumor-free tissue." (PMID 24939415, 2014). "In breast cancer cells, signaling is triggered by its receptor CD74, then channeled via the Akt pathway, with the involvement of Src and PI3K." (PMID 24939415, 2014). "To clarify the causal involvement of MIF in breast cancer, we investigated the role of MIF and its receptor CD74 in cytokine production, proliferation, and invasion of invasive versus non-invasive breast cancer cells." (PMID 19602265, 2009). "It is of note that the breast cancer cell type exhibiting the highest overall (surface + endolysosomal) CD74 expression levels, showed the greatest response to MIF." (PMID 19602265, 2009). "We found that anti-MIF and anti-CD74 antibodies potently blocked breast cancer cell proliferation induced by autocrine or exogenous MIF." (PMID 19602265, 2009). "CD74 promoted immunosuppressive tumor microenvironment formation in breast cancer in mice; therefore, CD74 might be considered a novel therapeutic target in breast cancer." (PMID 40427533, 2025). "Furthermore, AEP was found to enhance the metastatic and invasive ability of breast cancer cells through CD74 regulation." (PMID 40411322, 2025). "For example, one study demonstrated that CD74 is essential for the distant metastasis of breast cancer, and targeting CD74 therapy may be an effective strategy for breast cancer treatment." (PMID 40470045, 2025). "This study clarifies the molecular mechanism of AEP promoting breast cancer metastasis by regulating CD74, explores the therapeutic effect and safety of AEP and CD74 combined inhibition on breast cancer metastasis, and provides new targets and ideas for breast cancer metastasis treatment." (PMID 40411322, 2025). "Future experimental studies could focus on these three aspects to investigate the downstream molecular mechanisms of CD74 in breast cancer." (PMID 38582956, 2024).
breast carcinoma (continued). "Therefore, we strived to understand the possible physiological role of CD74 in solid tumors including breast cancer cells." (PMID 39056676, 2024). "Our results support the hypothesis that CD74 expressed in breast cancer is a marker of immune cell infiltration and longer survival." (PMID 34944801, 2021). "However, discordant results have been reported for immunohistochemical studies of CD74 expression in breast cancer." (PMID 34944801, 2021). "Immunotherapy holds great promise in clinical management of breast cancer, and CD74 may play a regulatory role in immune system responses." (PMID 34944801, 2021). "CD74 and MHCII expression is associated with patient survival in Basal-like breast cancer, and the association with TIL may reflect an effective intratumoral immune response." (PMID 27058619, 2017). "It was reported that MIF and CD74 are upregulated in subjects with breast cancer (BC)." (PMID 28477623, 2017). "Our IHC data showed that CD74 was highly expressed in breast cancer tissues." (PMID 27626171, 2016). "Powerful drugs and antibodies targeting CD74 may therefore be an effective novel strategy for breast cancer therapy." (PMID 27626171, 2016). "Our data showed that CD74 interacted with CD44 in breast cancer cells." (PMID 27626171, 2016). "Our findings uncover the molecular mechanism by which CD74 promotes breast cancer metastasis." (PMID 27626171, 2016). "According to our IHC data, CD74 is a marker of breast cancer metastasis." (PMID 27626171, 2016). "Moreover, RHOA is necessary for CFL1 phosphorylation and cell migration induced by CD74 in breast cancer cells." (PMID 27626171, 2016). "CD74 is thought to promote breast cancer metastasis, but the molecular mechanism remains elusive." (PMID 27626171, 2016). "Our findings highlight the critical role of CD74 in breast cancer metastasis." (PMID 27626171, 2016). "Since bevacizumab, an anti-VEGF antibody, appears to be more efficient in TRN breast cancer, stromal CD74 expression could be examined as a predictive marker of response to bevacizumab-based therapy." (PMID 24939415, 2014). "We suggest that, in breast cancer, high-level expression of CD74 could be a marker of increased vascularity in stroma." (PMID 24939415, 2014). "The role of MIF/CD74 in lung metastasis of breast cancer and whether the combination of MIF inhibitors and AEP inhibitors is safer and more effective than the chemotherapy drug combination regimen used in previous studies (AEP inhibitors + epirubicin) are still unknown." (PMID 40411322, 2025). "New drugs and antibodies targeting CD74 may be effective strategies for breast cancer therapy." (PMID 27626171, 2016). "In addition, CD74 interacts with CD44 which is highly expressed in breast cancer stem cells (CSC), hinting that CD74 may play a critical role in generation and maintenance of cancer stem cells (CSC) via regulating the function of CD44." (PMID 27626171, 2016). "Thus, CD74 appears to be primarily expressed in invasive breast cancer cells, indicating that such tumour cells may be prone to stimulation with MIF." (PMID 19602265, 2009). "Analysis of the correlation between CD74 and APP and breast cancer patient survival in the TCGA cohort revealed that higher CD74 levels were associated with significantly longer survival times." (PMID 40357856, 2025). "Subsequent in vitro experiments, including transwell migration and Western Blot experiments, demonstrated that the combined inhibition of AEP and CD74 reduces the migration ability and EMT level of breast cancer cells." (PMID 40411322, 2025). "Further investigations demonstrated that AEP activates ERK pathway phosphorylation via CD74 regulation, thereby enhancing epithelial‐mesenchymal transition (EMT) progression and promoting breast cancer cell migration." (PMID 40411322, 2025).
breast carcinoma (continued). "Therefore, combination therapy utilising AEP‐targeted inhibitors and CD74/MIF pathway inhibitors may provide comprehensive inhibition of distant organ metastasis in breast cancer, potentially emerging as a promising clinical strategy for future therapeutic development." (PMID 40411322, 2025). "In oncology, its identification of spatially resolved therapeutic targets—such as VEGFA and CD74 in glioblastoma, or ARL2 and TMEM145 in breast cancer—highlights its potential to uncover microenvironment-specific drivers of disease progression." (PMID 41275376, 2025). "Here, we introduced CD74 as one of those crucial inhibitors for FAS-mediated apoptosis and our results point to the possibility that the FAS pathway is synergized and activated by the CD74-derived peptide and AKT inhibitor in breast cancer." (PMID 39056676, 2024). "We show here that CD74 is involved in the internalization of TIMP‐1 by breast cancer cells and that TIMP‐1‐mediated activation of Akt signaling is dependent on CD74." (PMID 37081824, 2023). "CD74 is thought to promote breast cancer metastasis, so we decided to focus our attention on its putative interaction with TIMP‐1 in breast cancer cells." (PMID 37081824, 2023). "The first CD74 fusion protein, CD74-ROS1, was originally identified in NSCLC and 14 years later was also reported in breast cancer." (PMID 37958963, 2023). "We verified one of these interactors, CD74, as a TIMP‐1 cell surface binding protein in breast cancer cells." (PMID 37081824, 2023). "Similar to breast cancer, the majority of CTCs enriched from NSCLC-BM patient’s blood showed a strong expression for both CD74 (13/27 CTCs) and CD44 (15/27 CTCs)." (PMID 34209696, 2021). "The expression of both proteins showed a highly correlative expression, supporting the previously published data on a direct interaction between CD74 and CD44 in breast cancer." (PMID 34209696, 2021). "In the breast cancer BM cohort, all seven CTC positive patients showed a mostly strong or intermediate expression for CD74 (39/40 CTCs) as well as for CD44 (3/40 CTCs)." (PMID 34209696, 2021). "This is the first time that CD74 and CD44 colocalization has been quantified in breast cancer cells using a non-invasive and validated bioimaging procedure." (PMID 29190904, 2017). "We show that CD74 and CD44 molecules are detectable by flow cytometry in CAMA-1, MDA-MB-231 and MDA-MB-435 breast cancer cells." (PMID 29190904, 2017). "In summary, we demonstrate that CD74 promotes breast cancer cell metastasis, that CD74 and CD44 coordinately upregulate CFL1 phosphorylation through RHOA pathway, and that the repression of CD74 expression suppresses xenograft growth in vivo." (PMID 27626171, 2016). "Consistently, CD74 downregulation reduced MDA-MB-231 cell invasion and migration and suppressed protrusions in breast cancer cells." (PMID 27626171, 2016). "In conjunction, these experiments showed that proliferation of both non-invasive and invasive breast cancer cells is driven by autocrine MIF action, encompassing the secretion of endogenous MIF and signalling through MIF/CD74." (PMID 19602265, 2009). "Moreover, our findings establish that WISP1 enhances metastatic plasticity in ER+ breast cancer by amplifying MIF signaling and engaging Lyn/Fyn-mediated cytoskeletal remodeling, even in low-CD74 contexts." (PMID 41597235, 2026). "Specific ligand‐receptor interactions were observed between these epithelial subtypes and fibroblasts, with significant interactions between CD74‐APP receptors in SCGB3A1‐Epi and Fib‐11 in breast cancer and between SPP1‐CD44 receptors in KLK10‐Epi and Fib‐11 in PDAC." (PMID 40357856, 2025). "Transwell migration experiments verified these findings, indicating that the knockdown of CD74 can reverse the migration ability of breast cancer cells enhanced by AEP, suggesting that AEP can enhance the migration capability of breast cancer cells by regulating CD74." (PMID 40411322, 2025).
breast carcinoma (continued). "Additionally, the enzyme's influence extends to interactions between membrane CD74 and TIMP‐1 in breast cancer, promoting internalization and Akt signalling activation." (PMID 39074261, 2024). "Breast cancer is a highly heterogeneous disease and our data cannot unequivocally tell us whether the TIMP‐1/CD74 interaction is of pathophysiological relevance regarding tumor progression or response to treatment." (PMID 37081824, 2023). "To determine whether CD74 expression correlated with that of TIMP‐1 breast cance, we examined TIMP‐1, CD74, and CD63 protein levels in tumor cells in a set of 43 breast cancer tumors." (PMID 37081824, 2023). "Genes identified in breast cancer included ERBB3, LIV‐1 and SLC44A4; in colorectal cancer CD71, PTK7 and SLC44A4; in lung cancer SLC44A4; in prostate cancer LIV‐1 and PSMA; and finally in stomach cancer CD71 and CD74." (PMID 37740463, 2023). "Our study is the first to link CD74 and TSPAN7 expression with distant metastasis–free survival in breast cancer, highlighting gene signature based on CD74 and TSPAN7 as a predictor of metastasis development in BC, with a strong effect on patients’ distant metastasis–free survival." (PMID 36911401, 2023). "CD74-APP interaction was reported to ameliorate beta-amyloid production in Alzheimer’s disease, but in five out of six positive lymph nodes, we detected this interaction between TME macrophages and metastatic breast cancer cells." (PMID 36148946, 2022). "Breast cancer patient P6, a HER2 and hormone receptor-positive breast cancer patient (HER2+, ER+, PR+), with additional metastases in bone, lung and liver, had 16 detectable CTCs, all with a strong or intermediate expression of both CD74 and CD44." (PMID 34209696, 2021). "The most aggressive breast cancer cell lines MDA-MB-231, MDA-MB-436, and BT-474 have high levels of RIL expression concomitant with unfavorable prognostic parameters, such as the increased CD74 and low E-cadherin levels." (PMID 32002121, 2020). "Measuring the co-expression levels of CD74 and CD44 could potentially be used as a ‘biomarker signature’ to monitor different stages of breast cancer." (PMID 29190904, 2017). "Here we demonstrate clear heterotypic interaction between CD74 and CD44, which might act in synergy and hence contribute to breast cancer progression." (PMID 29190904, 2017). "In summary, measuring the co-expression levels of CD74 and CD44 could potentially be used as a ‘biomarker signature’ for examining different stages of breast cancer." (PMID 29190904, 2017). "We assessed CD74 and MHCII expression in tumor cells, as well as CD8, CD4, and CD68 tumor infiltrating leucocyte (TIL) density by immunohistochemistry in a cohort of 492 breast cancer patients." (PMID 27058619, 2017). "CD74 was not prognostic for relapse free survival (RFS) or overall breast cancer specific survival (OS) in the overall cohort." (PMID 27058619, 2017). "Although about 10-20% of breast cancers are triple negative, it would be of interest to study CD74 and CD44 in a cohort of breast cancer cells tested negative for estrogen receptors, progesterone receptor, and HER2." (PMID 29190904, 2017). "Moreover, CD74 overexpression promoted the phosphorylation of the actin-severing protein cofilin (CFL1), resulting in actin polymerization in breast cancer cells." (PMID 27626171, 2016). "Level of co-expression of MIF and CD74 could be a surrogate marker for efficacy of anti-angiogenic drugs, particularly in TRN breast cancer tumor." (PMID 24939415, 2014). "To date, co-expression of MIF and CD74 has not been studied in breast cancer but it has been described in prostate and non-small cell lung cancer." (PMID 24939415, 2014). "Level of co-expression of MIF and CD74 could be a surrogate marker for efficacy of anti-angiogenic drugs, particularly in TRN breast cancer tumors." (PMID 24939415, 2014).
breast carcinoma (continued). "CD74 is expressed on various cancer cells, i.e. prostate cancer cells, B lymphomas, or gastric carcinomas, but its expression in breast cancer has not been studied." (PMID 19602265, 2009). "This indicates that compared to BIC‐113 or ISO‐1 treatment alone, the combined inhibition of AEP and CD74 could better improve the prognosis of mice with lung metastasis from breast cancer and had no significant toxic effect on their weight." (PMID 40411322, 2025). "Thus, ADCs directed against SLC44A4 could potentially be evaluated in breast cancer; CD71, PTK7 and SLC44A4 in colorectal cancer; SLC44A4 in lung cancer; LIV‐1 in prostate cancer, and finally CD71 and CD74 in gastric cancer." (PMID 37740463, 2023). "Recently, CD74 has been described as having an oncogenic role in promoting cell proliferation and preventing cell death via a macrophage migratory inhibitory factor (MIF)-dependent manner, as proven in breast cancer, renal cell carcinoma, colorectal cancer, and non-small-cell lung carcinoma." (PMID 35208514, 2022). "Overall, our results indicate that CD74 may be a therapeutic target for the treatment of breast cancer patients, in particular in triple negative breast cancer and metastatic breast cancers, where CD74 is commonly overexpressed." (PMID 34944801, 2021). "Moreover, in primary breast cancer, a direct interaction between CD44 and CD74 has been described." (PMID 34209696, 2021). "Since CD74 expression may mediate both tumor promoting and anti-tumor effects in cancer cells, respectively, the outcome of CD74 overexpression in breast cancers is not easily predictable and may be contingent on multiple parameters." (PMID 34944801, 2021). "In breast cancer, correlations with good and poor prognosis have been reported for STAT1 expression, and high protein expression of STAT1 together with high levels of CD74 defined a subtype of triple negative breast cancer with increased invasiveness and metastatic potential." (PMID 32275681, 2020). "The present study has clearly demonstrated the occurrence of quantifiable colocalization between CD74 and CD44 in the plasma membrane of the breast cancer-derived cell lines CAMA-1, MDA-MB-231 and MDA-MB-435, suggesting interaction of these two molecules in breast cancer cells." (PMID 29190904, 2017). "It has been previously shown that MIF mediates CD74 induction for the regulation of the PI3K/AKT signaling, but the mechanism is not known in TNBC and breast cancer cells." (PMID 39056676, 2024). "The present study sought to characterize the cell-surface and total protein expression of CD74 and CD44 in three human breast cancer cell lines types (CAMA-1, MDA-MB-231, MDA-MB-435) and in normal luminal 226LDM cells." (PMID 29190904, 2017). "Breast cancer tissue of celecoxib-treated patients showed a significantly increased expression of MHC class II genes, including HLA-DRα and HLA-DRβ2, CD74 (MHC class II invariant chain) and HLA-DM, but not HLA-DQ and HLA-DOA." (PMID 23566419, 2013). "MIF was abundantly expressed in the non-invasive breast cancer cell lines MDA-MB-468 and ZR-75-1, but not in invasive MDA-MB-231 cells, which in turn expressed higher levels of the MIF-receptor CD74." (PMID 19602265, 2009).